CD4 (CD4 molecule)
Diseases named in the same sentence as CD4 in open-access papers (continued):
Sharing a sentence is not in itself a finding about the gene and the disease.
tumor (continued). "Regarding the route of plasmid administration, it was shown that IT IL-12 GET led to NK and CD8+ and CD4+ T cell accumulation and tumor elimination in murine squamous cell carcinoma." (PMID 34358144, 2021). "We revealed CD4+ naive T cells in the tumor core that express high levels of immune checkpoint molecules and have a higher activity of immune-exhaustion signaling." (PMID 34513820, 2021). "The expression of Smad7 in T cells led to an increase in the number of tumor-infiltrating T-bet/RORγ-t double-positive CD4+ T cells while decreasing the expression of IL-17A in CD+ T cells." (PMID 34059951, 2021). "TIMER database analysis showed positive correlation between the ten prognostic IRGs and the levels of tumor-infiltrated immune cells, including CD4+ and CD8+ T cells, macrophages, neutrophils, and dendritic cells." (PMID 33536348, 2021). "We then assessed functional profiles of tumor-infiltrated CD4+ and CD8+ T-cells and their expression of immune checkpoint molecules (PD-1 and CTLA-4)." (PMID 33391535, 2021). "Clinical studies demonstrate that CD4 T cells with anti-tumor reactivity can mediate their effects via direct cytotoxicity against tumor targets, and by broadening the CD8 T-cell response in the context of immunotherapy, such as with anti-CTLA-4 antibodies." (PMID 34201655, 2021). "In contrast, the combination of BD0801 and anti-PD-L1 antibody increased the percentage of tumor-infiltrated CD4+ and CD8+ cells compared to vehicle or single treatment groups." (PMID 34686154, 2021). "A higher density of CD4+ T-regulatory and TH2-helper cells, paucity of CD8+ T-cells and lower mutational burden are associated with impaired anti-tumour immunity and shorter survival rates." (PMID 33546207, 2021). "It is known that CD4+ T-cells mediate systemic immunity, which is important for long-term tumor elimination." (PMID 34926461, 2021). "It protects tumor cells by regulating CD4+ T, CD8+ T and NK cells to produce immunosuppressive effects." (PMID 34938753, 2021). "Although I didn’t isolate Tr1 cells in this investigation, several previous studies also point out the importance of IL-10-secreting Tr1 CD4 T cells for tumor immunity." (PMID 33912464, 2021). "A caveat of the CD4+ immune response is the different subtypes that are considered good or bad with respect to anti-tumor immunity." (PMID 34290704, 2021). "We will explore other T cells such as CD4 T cell, type 1 T cell, regulatory T cell and so on in next study on tumor‐infiltrating T cells in HGSOC." (PMID 33955198, 2021). "For example, IL-35 suppressed the effector functions of CD4+ cells and favored tumor growth by facilitating the exhaustion of CD8+ T cells." (PMID 33418929, 2021). "Decreased tumor growth and weight was also observed in mice treated with CD26high T cells compared to mice treated with CD4+ or CD26neg T cells." (PMID 33407605, 2021). "IN_in_r1 induces a preferable profile of immune response rich in IFN-γ/TNF-α/IL-2 and IFN-γ/IL-2/GrB producing CD8+ T cells, and IFN-γ/TNF-α and IFN-γ/IL-2/TNF-α producing CD4+ T cells, allowing better control of tumor cell challenge." (PMID 34199989, 2021). "Further analysis revealed that a high expression of RFC4 also indicates poor prognosis, even when accompanied by high levels of tumor-infiltrating immune cells, including CD4+ T cells, CD8+ T cells, B cells, dendritic cells and monocytes." (PMID 34520390, 2021). "Here, we found a diet-dependent positive relationship between FoxP3+CD4+ Treg cells and primary tumor area or advanced metastases." (PMID 34707136, 2021). "Consistently, we found higher CD8+ and CD4+ T-cell infiltration in HNSCC tumor tissues than adjacent normal tissues (p < 0.05) in our cohort." (PMID 35087741, 2021). "Genome wide methylation sequencing showed 13571 uniquely differentially methylated regions (DMR), mostly concentrated around the TSS, in the CD4+ T cells from GBM patient tumor compared to blood." (PMID 34012510, 2021).
tumor (continued). "C5aR can also facilitate tumor metastasis by suppressing the response of CD4+ and CD8+ T cells in the lung, possibly driven by the recruitment of immature myeloid cells to the lungs and the production of large amounts of TGF-β and IL10." (PMID 34688269, 2021). "The risk score was significantly correlated with the proportions of CD8+ T cells, CD4+ memory resting T cells, follicular helper T cells, memory B cells, plasma cells, and M2 macrophages in tumor tissues." (PMID 34746127, 2021). "BT942 resulted in a higher expansion of CD8+ T cells and CD4+ T cells in tumor microenvironment in mouse MC38 model compared to BA9." (PMID 34824364, 2021). "In the treatment of Lewis lung tumor with radiotherapy, tumor-infiltrating CD4+CD25+ Treg and CCL2 levels decrease, while miR-545 levels increase." (PMID 34084160, 2021). "Treatment with CuCo(O)/GOx@PCNs significantly increased CD8+ T cells and CD4+ T cells in primary tumor tissues, suggesting decreased regulatory T cells (Treg cells)." (PMID 34656118, 2021). "On the other side, tumor antigens can also be presented by bystander antigen presenting cells (APCs) via MHC II complexes to CD4+ T cells in tumors." (PMID 34135885, 2021). "In CLL, in vitro and xenograft murine models have demonstrated a pro-tumor effect of the CD4+ T cell compartment in patients, with correlations of CD4+ subset counts and clinical outcome supporting this role." (PMID 33842331, 2021). "In this work, we have revealed a significant CD4+ Th response to tumor lysate, while the cytotoxic response of CD8+ lymphocytes is not prominent." (PMID 34576023, 2021). "Specifically, we identified CD117+ granulocytes and CD45RO+ CD4+ memory T cells correlating with the presence of the primary tumor and radiotherapy, respectively." (PMID 34090509, 2021). "Compared with adjacent normal lung tissues, an increased proportion of CD45+ hematopoietic-derived cells was observed in tumor samples, and CD4+ T cells were found to be the largest cell population in the TILs." (PMID 33747957, 2021). "Our results demonstrated that plasma cells, CD8+ T cells, M1 macrophages, NK cells, Treg cells and CD4+ memory T cells were crucial determinants of tumor metastasis, consistent with previous reports." (PMID 33203789, 2020). "Here, we showed that induction of CD39 on CD4+ T cells by total plasma-derived exosomes was dependent on the tumor stage at which exosomes were isolated." (PMID 32708274, 2020). "Our findings underscore the role of Treg cells, IL-2, and Blimp-1 in controlling the differentiation of cytotoxic CD4+ T cells and offer a pathway to enhancement of anti-tumor activity through their manipulation." (PMID 31924474, 2020). "Of note, we detected CD8+ PD‐1+ cells in the stroma as well as in the actual tumor nodules, while CD4+ PD‐1+ exclusively localized to the tumor microenvironment." (PMID 32615027, 2020). "MOC1 is an indolent tumor with infiltration of CD4+ and CD8+ T cells and is partially responsive to anti-PD-L1 mAb." (PMID 32295135, 2020). "CD4+PD‐1hi T cells with possible immune suppressive effects on CD8+ T cells have been shown to accumulate in the lung as a function of tumour burden, and inhibit effector T cell functions." (PMID 33015859, 2020). "Caserta at al. reported that IL-7 was superior to IL-2 for expansion of tumour-reactive CD4+ T cells." (PMID 32183246, 2020). "In NSCLC, interaction of CD161 expressing tumor infiltrating CD4+ and CD8+ T cells with LLT1-expressing germinal center B cells within tumor microenvironment tertiary lymphoid structures resulted in improved survival." (PMID 33597948, 2020). "BMP7 secreted by tumor cells acts on macrophages and CD4+ T cells in the tumor microenvironment, inhibiting MAPK14 expression and impairing pro-inflammatory responses." (PMID 32973129, 2020). "The infiltration of cellular sources of IL-22 including Th22 and CD4+ T cells in the intratumoral tissue increases, corresponding to the stage of tumor." (PMID 33042126, 2020).
tumor (continued). "In different experimental systems, MDSCs are able to blunt IFN-γ production of both tumor-specific CD8+ and CD4+ T cells in the spleen of tumor-bearing mice in vivo." (PMID 32793192, 2020). "There, activated CD8+ T cells can recognize and kill tumor cells, while CD4+ T cells exhibit diverse functions that support an anti-tumor immune response." (PMID 33207601, 2020). "When combined with anti-PD1 therapy, this strategy significantly delayed tumor progression in 4T1 and B16 melanoma tumor models with a substantial increase in infiltrated antitumor CD8+/CD4+ T cells and NK cells and a reduced population of T-regs in the TME." (PMID 32424240, 2020). "Mice restricting tumor growth were characterized by high percent of CD4+ and CD8+ T cells responding to TERT6 and TERT8 by multicytokine production." (PMID 32570805, 2020). "The proportion of CD4+CD25+Foxp3+ Treg in transplanted tumor tissues was detected by flow cytometry." (PMID 33204731, 2020). "We observed tumor growth control in spite of depletion of circulating CD8+ or CD4+ T cells (bottom), seen also by the percentage of tumor-free mice." (PMID 33240271, 2020). "They promote tumor extravasation and angiogenesis, suppress the immune system, and recruit CD4+T cells, and so promote tumor growth and metastasis." (PMID 31741042, 2020). "Our model, instead, was based on the “physiological” expression of MHC-II molecules and, consequently, on the idea of classical MHC-II-restricted presentation of tumor antigen peptides to CD4+ Th cells." (PMID 33138029, 2020). "CCL5, secreted by tumor-infiltrating CD4 T cells, also facilitates the FAS-FASLG mediated CD8 T-cell apoptosis in gastric cancer." (PMID 33381115, 2020). "Noticeably, blood drawn from these two mice that were tumor free over 3 months exhibited an increase of memory T cells including effector/central memory CD8+ and central memory CD4+ T cells compared to control tumor mice." (PMID 33628206, 2020). "The YAP CD4 Cre mice always had a more dramatic anti-tumor phenotype across several subcutaneous murine tumor models, including MC38 and EL4." (PMID 32322254, 2020). "MHC class II protein complex, a molecule distributed to APC and activated T cell, plays an important role in the indirect activation of CD8+ T cells by presenting the tumor antigen to CD4+ T cells." (PMID 32931665, 2020). "When DC1s are stimulated with tumor TNF-α acquire the capacity to induce the differentiation of naïve CD4+CD45RA+ T-cell to Th1 cells." (PMID 32731512, 2020). "High CD4/CD3 stromal ratios and high infiltrates of tumor-associated macrophages were associated with reduced overall survival." (PMID 32658932, 2020). "In EOC, CD8 and CD4 T-cells infiltrate tumor tissues and ascites, and exert antitumor functions through specific recognition of tumor antigens (TA)." (PMID 32630708, 2020). "B16F10-derived exosomes can also activate the mitochondrial apoptotic pathway of CD4+ T cells in vitro and in vivo, thereby increasing tumour growth and reducing T cell infiltration." (PMID 32858889, 2020). "We further compared antitumor activity of STEAP130-TCR transgenic (tg) CD4+ versus CD8+ T cells in tumor-bearing xenografted Rag2−/−γc−/− mice." (PMID 32610710, 2020). "The number of CD4 + cells in distant tumours among rats in the RFA-only and OK-432 groups was also significantly higher than that among rats in the control group on days 30 and 51 (all P < 0.001)." (PMID 32541941, 2020). "Naïve CD4 T cells recognize tumor antigens similarly to CD8 T cells, but differing in the mode of presentation by APCs (MHC-II versus MHC-I)." (PMID 32244396, 2020). "Overall, most studies have broadly found equivalent changes in CD8 and CD4 T cells during anti-tumor responses." (PMID 32244396, 2020). "The immunosuppressive features of the Tregs among tumor-infiltrating CD4+ T cells in human PDAC were acknowledged by several other studies." (PMID 32397303, 2020).
tumor (continued). "Gating for both markers revealed that cytotoxic CD8+ T cells were slightly lowered in the skin of tumor‐bearing mice, whereas the CD4+ T cell population stayed unaffected." (PMID 32615027, 2020). "Our previous work has demonstrated that CD4+ T cells are distributed at higher numbers in the peripheral blood and tumor tissues of OC patients and are positively related to clinicopathological parameters." (PMID 33102225, 2020). "Dietary restriction also induces sirtuin 1 activity, which can support anti-tumor function in CD4+ T cells." (PMID 33170123, 2020). "Tumor antigens are recognized and processed by APCs which present these antigens to CD4+ T cells in the lymph nodes." (PMID 32636725, 2020). "Compared to Colon-26, not only MMPs but also T cell surface marker expression, such as CD4 and CD8a, had increased on Colon-26MGS tumor (Table A4)." (PMID 32325684, 2020). "Depletion of CD4+ TH1 cells decreases pericyte coverage and increases malformed tumor vessels in multiple mouse tumor models, whereas activation of CD4+ T cells improves vessel normalization." (PMID 32913278, 2020). "It was demonstrated that cDC2s lose their ability to induce CD4+ T cell differentiation during tumor growth." (PMID 33228747, 2020). "In contrast, group 1 patients with lower disease burden and slower tumor growth kinetics had less suppressive Th2 driven cytokine responses and specifically IL‐10, and expanded CD4+ effector T cells in response to treatment." (PMID 32578964, 2020). "Although NK cell depletion did not interfere with the antitumor activity of the combination therapy, a delay in the tumor growth was observed when antibodies depleting CD4+ T cells were administered." (PMID 33126649, 2020). "The present study showed that, compared with untreated tumor-burdened mice, the numbers of CD4+ and CD8+ T cells in the spleen and liver increased significantly after treatment with low-dose CTX." (PMID 32104586, 2020). "For instance, anlotinib treatment increased the INF-γexpression in CD4+ T cells and upregulated the tumor-infiltrating NK cells." (PMID 33680942, 2020). "Further, these inhibitors suppress CD4+ T regulatory cells proliferation, increase tumor immunogenicity and promote the cytotoxic response by T cells enhancing tumor cells clearance." (PMID 32366056, 2020). "We estimated the relationship between the abundance of six types of tumor-infiltrating immune cells (B cells, CD4+ T cells, CD8+ T cells, dendritic cells, macrophages, and neutrophils) and the signature risk score in MIBC." (PMID 33456631, 2020). "In the first phase, tumor cells are eliminated by cells of the immune system (NK cells, CD4+ and CD8+ T-lymphocytes)." (PMID 33348704, 2020). "CD4 T cells act on tumor immunity by secreting various cytokines or by activating other immune cells." (PMID 33816214, 2020). "rV-neuT+CUR-treated mice showed an increased infiltration of CD4+/CD8+ T lymphocytes within the tumor as compared to those that received the individual treatment." (PMID 32423101, 2020). "We defined malignant and stromal components of the TME by established gene signatures to characterize tumor cells, TAMs, CD4+ and CD8+ T cells, B cells, and CAFs." (PMID 33117401, 2020). "Since A20 tumor cells are derived from transformed B cells, they express high levels of MHC-II, making them susceptible to CD4+ T cell-mediated recognition." (PMID 33268774, 2020). "The results showed that tumor growth presented the greatest delay under treatment with Th9 cells compared with all the other CD4+ T cell subsets, including Th1 and Th17 cells." (PMID 32508847, 2020). "The expression level and in situ localization of miR-18a and -18b was assessed with respect to the presence of tumour infiltrating lymphocytes (TILs) and immunohistochemical markers for ER, CD4, CD8, CD20, CD68, CD138, PAX5 and actin." (PMID 32370743, 2020).
tumor (continued). "To verify that IFI44 was closely related to the infiltration of CD4+ T lymphocytes in the tumor area, we then explored the relationship between 66 core genes and CD4+/CD8+ cells using TIMER database." (PMID 33123469, 2020). "Immune profiles within T1 and T2 tumors and in spleen changed drastically with tumor burden in untreated mice with infiltrating CD4+ content declining, while the proportion of CD4+ Tregs rose." (PMID 32197352, 2020). "TILs are very heterogeneous, consisting of CD8+ T cells, CD4+ helper T cells, regulatory T cells, and B cells, as well as other subtypes of immune cells in the tumor microenvironment." (PMID 32894006, 2020). "Thirdly, the CD4-GZMA cell subset showed great prognostic value combined with their different abundance between tumor and normal tissues." (PMID 33043022, 2020). "CD4+/CD8+ cells are likewise elevated in the tumour draining lymph node and activated to a greater extent than individual treatments." (PMID 32243973, 2020). "The induction of antigen-specific responses by DEVs has been demonstrated by the activation of tumor-specific CD4+ and CD8+ T cells via engagement of their TCR and is superior to the induction of T cell responses by TDEVs." (PMID 33260499, 2020). "CD4+ T lymphocytes enhance tumor antigen-specific immune responses by producing cytokines, and CD8+ T cells provide key adaptive anti-tumor immunity through their production of IFN-γ and cytolytic activity." (PMID 33267869, 2020). "Despite the variable mutational load across different human malignancies and the technical challenges, tumor-infiltrating, as well as circulating, neoantigen-specific CD8+ and CD4+ T-cells have now been identified and characterized in several tumor types." (PMID 32695101, 2020). "Tumor-derived sEVs are carriers that efficiently transfer TAAs to DCs and induce antigen-specific CD4+ and CD8+ T cell activation via reprocessing." (PMID 32308755, 2020). "Correspondingly, we observed increased tumor infiltrated CD4+CD44+ and CD8+CD44+ T cells upon Bcl6 deletion in Treg cells." (PMID 32477338, 2020). "Cancer vaccines using synthetic long peptides (SLP) targeting tumor antigens have been tested in the clinic but the outcomes have been unimpressive, perhaps because these peptides elicit predominantly CD4+ T cell responses." (PMID 33298945, 2020). "In this study, we investigated the phenotypic and transcriptomic characteristics of tumor-infiltrating CD4+TIM-3+ T cells in CRC patients." (PMID 32041340, 2020). "The systemic expansion of a CD4+ CD62Llow CD27- FOXP3- CD44+ CXCR3+ ICOS+ T-bet+ T cell subset in mice treated with anti-cancer cell immunoglobulins was correlated with tumor rejection." (PMID 33329566, 2020). "It has been reported that this therapeutic strategy enhances the density of tumor-infiltrating CD4+ T cells expressing the costimulatory molecule inducible T cell costimulator (ICOS)." (PMID 32194568, 2020). "Administration of Y‐27632 into immunocompetent Balb/c mice bearing breast tumors suppressed tumor progression and enhanced CD4+ and CD8+ T‐cell infiltration." (PMID 32941674, 2020). "The proportion of CD4+ and CD8+ TILs in distinct tumour tissues is different, CD4+ TILs are related to humoral immunity, CD8+ TILs are related to cellular immunity, and CD8+ TILs play a major killing role in NSCLC." (PMID 33170901, 2020). "On the side of immunization, high level of RNF183 in UCEC is negatively related to tumor purity, infiltrating levels of CD4 + T cells, neutrophils, and dendritic cells." (PMID 33324448, 2020). "Contrary to PD-1, PD-L1 is expressed at the basal level on many cell types, such as CD4+ and CD8+ T lymphocytes, tumor cells, CAFs and Tumor-associated macrophages (TAMs)." (PMID 33261061, 2020).